ROS1 (ROS proto-oncogene 1, receptor tyrosine kinase)
Diseases named in the same sentence as ROS1 in open-access papers (continued):
Sharing a sentence is not in itself a finding about the gene and the disease.
lung cancer (continued). "This article describes a practical approach for the selection of initial and subsequent therapies for metastatic ROS1+ non–small cell lung cancer, explores the evolving evidence for optimal treatment of early-stage disease, and highlights areas for future research." (PMID 39177972, 2024). "It is questionable whether patients with other targetable/driver mutations, such as ROS1 or RET, should be treated with NA ICI-chemo, based on data showing the limited efficacy of immunotherapy in patients with advanced lung cancer who have these mutations." (PMID 38610980, 2024). "Based on assay design and coverage of key intronic regions of the genome, we were also able to detect a broad range of clinically relevant fusions, such as EML4::ALK, RET, and ROS1 rearrangements with diverse gene partners in lung carcinomas, BRAF::KIAA1549 and EGFRvIII alterations in gliomas." (PMID 39289779, 2024). "But there is now a growing interest for the prevalence of ROS1 fusions in early-stage lung cancer." (PMID 37237384, 2023). "In early-stage lung cancer ROS1 might also provide a fruitful target for neoadjuvant or adjuvant therapy." (PMID 37237384, 2023). "Recent studies reported that patients with EGFR/ALK/ROS1 mutation, bone metastasis, and no immune-related adverse events had poor prognosis during immunotherapy in lung cancer." (PMID 37790758, 2023). "Lung cancer is driven by different molecular alterations, including the epidermal growth factor receptor (EGFR) mutations and the rearrangements of the anaplastic lymphoma kinase (ALK) and the c-ros1 (ROS1) genes." (PMID 37340403, 2023). "ROS1 has also been found to be overexpressed in oral carcinoma and lung cancer tissue." (PMID 37958963, 2023). "It is important to note that other relevant mutations typically associated with lung cancer (such as ALK, ROS1, RET, FGFR1, ERBB2, etc.)have been found with frequencies compatible with previously published data, but without a significant difference between subgroups." (PMID 37173325, 2023). "Although tyrosine kinase inhibitor (TKI) therapy shows marked clinical efficacy in patients with anaplastic lymphoma kinase–positive (ALK+) and ROS proto-oncogene 1–positive (ROS1+) non–small cell lung cancer (NSCLC), most of these patients eventually relapse with acquired resistance." (PMID 37917191, 2023). "This budget may double in the case of NSCLC analysis, because lung carcinomas have to be additionally tested for EGFR, BRAF, KRAS, MET, and HER2 mutations as well as ALK, ROS1, and RET translocations." (PMID 37762506, 2023). "Mutations in lung cancer driver genes (KRAS, EGFR, BRAF, ALK, ROS1, MET, RET, and ERBB2) in the high- and low-risk groups were shown on a waterfall plot, which demonstrated that the low-risk group (20%) harbored a higher EGFR mutation frequency than did the high-risk group (8%)." (PMID 36353226, 2022). "Overall, only a small proportion of EGFR wild-type lung cancers harbored ROS1 translocation." (PMID 35628598, 2022). "Among the detected alternations, the eight-major driver mutations of lung cancer (EGFR, ALK, ERBB2, MET, RET, ROS1, BRAF, and KRAS) could be found in 14 out of 17 (82.4%) patients using both surgical and CNB specimens." (PMID 36224661, 2022). "Besides the sensitive detection of SNVs and INDELs, gene fusions in ALK, RET, or ROS1 were detected in 2.9% of ctDNA-positive lung cancer cases, exemplifying the clinical applicability of an amplicon-based assay for the detection of novel fusions." (PMID 35486650, 2022). "Likewise, a study involving 7858 lung cancer patients which compared mutations between patients aged ≤45 vs >45 years observed a higher prevalence of ALK, ROS1 and RET fusions, ERBB2 exon-20 insertions and EGFR exon-19 deletions in younger patients." (PMID 36263208, 2022). "ROS1 translocated lung cancer is an independent poor prognostic overall survival factor and could be reversed by crizotinib treatment." (PMID 35628598, 2022).
lung cancer (continued). "METex14 skipping mutation is considered to be an independent lung cancer driver, which is usually mutually exclusive with other lung cancer driver genes such as EGFR, ALK and ROS1, and is also associated with poor prognosis of lung cancer, including sarcomatoid cancer." (PMID 36212500, 2022). "Non-lung cancers were more likely to harbor rare ROS1 fusions (Bonferroni’s post-test, P = 0.002)." (PMID 36369474, 2022). "Our results indicated that two patients with lung cancer harbored two ROS1 fusions." (PMID 36589752, 2022). "Similar GOPC–ROS1 fusions have been seen in pediatric gliomas and adult lung cancers and may be sensitive to ROS1 inhibitors." (PMID 35787784, 2022). "When the drug resistance of crizotinib and entrectinib is ROS1-G2032R mutation mediated by nontargeted drug resistance, lorlatinib can be used as the second-line treatment for ROS1-rearranged lung cancer, which can appropriately prolong the progression-free survival time of patients." (PMID 34976824, 2021). "ROS1 is important in lung cancer with a correlative relationship to PD-L1 expression." (PMID 33407928, 2021). "Similarly, YAP1 activation is a mechanism of resistance to crizotinib therapy for ROS1-rearranged lung cancers." (PMID 34685695, 2021). "These targetable RTK rearrangements consist of ALK fusion in lung cancer and anaplastic large cell lymphoma, ROS1 fusion in lung cancer and glioblastoma, RET fusion in lung and thyroid cancer, FGFR fusion in bile duct and urothelial carcinoma, as well as NTRK fusion in pan-cancer." (PMID 34650924, 2021). "The first report of ROS1 rearrangements in lung cancer dates back to 2007." (PMID 34884672, 2021). "ROS1 IHC can be performed on cytological specimen as well as on formalin-fixed paraffin-embedded (FFPE) tissue specimen or on cellblocks that are often used in lung cancer diagnosis." (PMID 34884672, 2021). "Moreover, patients with ALK-positive lung cancer have a higher incidence of brain metastasis, whereas patients with ROS1-positive lung cancer have a lower incidence." (PMID 34205733, 2021). "Improved understanding of the biology of lung cancer has resulted in the development of new biomarker-directed therapies targeting molecular alterations (eg, EGFR mutations, ALK rearrangements, ROS1 rearrangements, and BRAF V600E mutations), which have prolonged survival of lung cancer patients." (PMID 33442422, 2021). "Moreover, finding target molecules, such as epidermal growth factor receptor (EGFR), anaplastic lymphoma kinase (ALK), ROS1, and programmed death ligand 1 (PD-L1), is significantly important for making treatment decisions in patients with lung cancer." (PMID 34441366, 2021). "Interestingly, these fusion mutation mechanisms of resistance, both on target and off-target, were described analogously in other cancer types such as ALK fusion-positive lung cancer and ROS1 fusion-positive lung cancer." (PMID 34829820, 2021). "The high fraction of patients harboring either EGFR and ROS1 positivity led authors to speculate that ROS1-rearranged and EGFR-mutated lung cancer may originate from a common precursor lesion." (PMID 34884672, 2021). "Currently, lung cancers are screened for actionable mutations, to identify cases suitable for targeted therapies, including those targeting mutations in EGFR, BRAF and rearrangements in ALK or ROS1." (PMID 32898185, 2020). "ROS1 gene fusion represents a specific subtype of non‐small cell lung cancer (NSCLC)." (PMID 32168429, 2020). "Tumors with mutations in BRAF (7% of lung cancers) may be treated with vemurafenib or dabrafenib, and tumors with rearrangements involving ALK and/or ROS1 (1–2% of lung cancers) may be treated with crizotinib, ceritinib or alectinib." (PMID 32898185, 2020). "Activating EGFR mutations are found in about 15% of NSCLC, while ALK and ROS1 alterations are quite rare ( < 5% of lung cancers) but are frequent among light to never smokers." (PMID 32604993, 2020).
lung cancer (continued). "Our results also indicate that ROS1 fusion NSCLCs show a beneficial ICI therapy response, which lessens in ROS1 G2032R resistance mutation, thus implying that driver genes should be considered when conducting anti-PD-L1/PD-1 ICI therapy to manage lung cancer treatment." (PMID 33324391, 2020). "Additionally, a novel ROS1-ADGRG6 rearrangement induced by the fusion of exons 1–33 of ROS1 on chr6 to exons of 2–26 of ADGRG6 on chr6 has been previously reported in lung cancer." (PMID 32322582, 2020). "However, crizotinib resistance often occurs, making the treatment of ROS1-positive lung cancers more challenging." (PMID 33172113, 2020). "For instance, EGFR, ALK, and ROS1 tyrosine kinase inhibitors against tumors with EGFR mutations, ALK fusions, and ROS1 fusions respectively, are already in use as standard treatments in lung cancer in clinical settings." (PMID 33264103, 2020). "ROS1 is rearranged with genes such as SCL34A2 or CD73 in approximately 1% of lung cancers." (PMID 30943926, 2019). "Therefore, further studies using a larger panel with various types of lung cancer cell lines and tissues would be useful to elucidate the causes of discordance in clinical ALK or ROS1 IHC tests." (PMID 30943926, 2019). "We demonstrated that the transcription levels of ALK- or RET-fusion partner genes, such as EML4, CCDC6 and KIF5B, were constitutively activated in lung cancer cells, and the expression at the C-terminal region of ALK, RET, or ROS1 was also markedly elevated in each fusion-positive lung cancer cell." (PMID 30943926, 2019). "Due to the low occurrence probability of ROS1 fusion in lung cancer patients, this molecular subtype was often neglected in the past in clinical practice, and patients with ROS1 fusion were often treated with standard regimens such as chemotherapy for first-line." (PMID 30930778, 2019). "C-ros oncogene 1 (ROS1) rearrangement is a driver oncogene in lung cancer." (PMID 30443294, 2018). "Similarly, in KRAS-mutant lung cancers, PFS (5.0 months, 95% CI 3.67–6.33) was inferior compared with EGFR-mutant (6.5 months, p = 0.242) and ALK/ROS1-rearranged (9.2 months, p = 0.007) lung cancers." (PMID 29587667, 2018). "These Hsp90 inhibitors suppressed ROS1 phosphorylation in wild-type CD74-ROS1, F2004V-, or F2075C-mutated cells similarly to what has been observed in ROS1-rearranged lung cancer cells." (PMID 28717217, 2017). "In 4 patients with lung cancer, ROS1 copy numbers were heterogeneous between CTCs." (PMID 26980749, 2016). "One example of altered TKR is the ROS1 gene, which has been proved to be involved in lung cancer." (PMID 27528792, 2016). "Interestingly, ROS1 expression levels in ROS1-positive lung cancers and cell lines can vary from cell to cell, suggesting dynamic ROS1 protein expression despite homogeneous presence of ROS1 gene rearrangement." (PMID 27535289, 2016). "We suppose that histology of ROS1+ lung cancer has low differentiation with peculiar immunoprofile, which may indicate that the cell of origin of ROS1+ lung adenocarcinoma may different from most lung adenocarcinomas." (PMID 27708233, 2016). "We analyzed 214 mutations across 26 lung cancer-associated genes and three fusion genes using the MassARRAY® LungCarta Panel and the ALK, ROS1, and RET fusion assays in 198 consecutively resected lung adenocarcinomas from never-smoker females at a single institution." (PMID 25760072, 2015). "However, due to the low frequency of ROS1 fusion in lung cancers, efficient determination of ROS1 status in NSCLC patients is critical for directing patient care." (PMID 25742289, 2015). "As knowledge of possible mechanisms of resistance could help in defining strategies aimed at either preventing or overcoming resistance, we generated ROS1+ HCC78 lung cancer cell resistant to ROS1 inhibitors." (PMID 25691052, 2015). "The ROS1 tyrosine kinase is activated in lung cancer as a consequence of chromosomal rearrangement." (PMID 25691052, 2015).
lung cancer (continued). "Because the ROS1 and Anaplastic Lymphoma Kinase (ALK) domains are partially homologous, the Food and Drug Administration (FDA)-approved ALK/MET kinase inhibitor crizotinib is being investigated via phase I/II clinical trials for its efficacy in ROS1-driven lung cancer patients." (PMID 25978031, 2015). "Recently, we investigated histopathology of ROS1-fusion positive human lung cancers." (PMID 23418494, 2013). "ROS1 rearrangements also define a unique molecular subclass of lung cancer that may respond to an ALK inhibitor." (PMID 24261984, 2013). "In addition, RBA nominated 6 other candidate ROS1 rearrangements, in breast cancer (BT-549, HS578t), glioblastoma (SF-295, U251), lung cancer (HOP-62), and angiosarcoma (AS1)." (PMID 23637631, 2013). "Given the increasing reliance on genetic and biomarker testing (EGFR, ALK, ROS1, PD-L1, and KRAS mutations) for targeted treatments, the ability to perform molecular analysis on minimally invasive samples represents a significant advancement in lung cancer care." (PMID 40805957, 2025). "In a previous study conducted by the University of California Lung Cancer Consortium, 54.9% of patients had EGFR mutations, 32.9% of patients had KRAS mutations, 5.3% of patients had ALK fusions, and < 3% of patients had other mutations (HER2, MET, RET, ROS1, or BRAF-non-V600E)." (PMID 39009968, 2024). "For instance, it was reported that for lung carcinoma, the rate of EGFR testing was the highest (>80%) while the rates of ALK and ROS1 testing were remarkably lower, despite the fact that ALK and ROS1 mutations could occur in up to 10% of the cases." (PMID 38404964, 2024). "However, it will not be pragmatically feasible to perform phase Ib/II clinical trials of discrete combination regimens for each individual therapy-resistant, rare molecular subset of lung cancer (e.g., ROS1-, RET-, and NTRK1-3-rearranged NSCLC) and for each distinct genomic mechanism of resistance." (PMID 37923925, 2023). "In this study we aimed to map the prevalence of ROS1 rearrangement in a Norwegian cohort of early-stage resectable lung cancer, and see whether the tumours with ROS1 fusion or ROS1 protein expression were associated with specific epidemiological, histological or genetic characteristics." (PMID 37237384, 2023). "However, although the determination of ROS1 is mandatory according to guidelines, real-world evidence obtained from Lung Cancer Biomarker Testing Registry (LungPath) show that ROS1 fusions were not determined in almost half of the samples of patients with NSCLC (testing rate: 58.1%)." (PMID 35303812, 2022). "In addition, fusions in ALK (overall, Fisher’s exact test P < 0.0001; lung cancer, P < 0.0001), ROS1 (overall, Fisher’s exact test P < 0.0001; lung cancer, P < 0.0001) and RET (overall, Fisher’s exact test P = 0.006; lung cancer, P < 0.0001) were associated with an earlier disease onset." (PMID 36369474, 2022). "In treatment-naïve lung cancer, oncogenic driver mutations, such as epidermal growth factor receptor (EGFR), Kirsten rat sarcoma virus (KRAS), BRAF, anaplastic lymphoma kinase (ALK), and ROS1, typically occur as trunk mutations with little intratumoral heterogeneity." (PMID 35008406, 2022). "In addition, two patients with lung cancer harbored two ROS1 fusions." (PMID 36589752, 2022). "Patients with small cell lung cancer and mutation-rich non–small cell lung cancer (eg, epidermal growth factor receptor, anaplastic lymphoma kinase, ROS-1) could not be separated." (PMID 34342588, 2021). "Therefore, it is possible that the NK cell activation and γδ T cell expansion that are mediated by ROS1 electrovaccination may prolong their functionality and contribute to lung cancer impairment." (PMID 32268572, 2020).
lung cancer (continued). "Interestingly, these mutations are paralogous to resistance mutations that have been identified after progression on ALK tyrosine kinase inhibitor therapy in ALK fusion-positive lung cancers, and ROS1 tyrosine kinase inhibitor therapy in ROS1 fusion-positive lung cancers." (PMID 31738426, 2019). "Moreover, high levels of MET amplification defined as MET:CEP7 > 5 were previously identified as actionable driver mutations predicting sensitivity of the tumor to the inhibitors of kinase MET, including crizotinib, currently approved for the treatment of ALK or ROS1-rearranged lung cancers." (PMID 28137276, 2017). "In addition to the current cornerstones of targeted therapy in NSCLC, EGFR mutations and ALK gene fusions, a growing number of alterations, like ROS1 gene fusions, are emerging as treatment predictive in lung cancer broadening the cohort of patients eligible for targeted treatment." (PMID 28415793, 2017). "Furthermore, ROS1 rearrangements were found in CTCs of four patients with lung cancer." (PMID 26980749, 2016). "Our mouse model of EZR-ROS1 lung cancer generally demonstrated papillary/lepidic growth pattern, but in some cases, we observed accumulation of cytoplasmic mucin in tumor cells, which quite resembles to the characteristic histology reported in ROS1-rearranged lung cancer." (PMID 23418494, 2013). "Thus, our EZR-ROS1 lung cancer animal model could be valuable for evaluating the therapeutic potential of these compounds and novel drugs as well as biological features of ROS1-rearranged lung cancer in vivo." (PMID 23418494, 2013). "In addition, ALK/MET inhibitor crizotinib also inhibited growth of HCC78- and ROS1-positive tumors suggesting that lung cancer patients with ROS1 rearrangement could benefit from targeted therapy using crizotinib." (PMID 22928112, 2012). "EML4-ALK fusions, RET rearrangements, ROS1 fusions, and NTRK1/2/3 fusions are observed at a cumulative frequency of 3 %–10 % in lung cancers." (PMID 40503459, 2025). "The discovery of therapeutically targetable gene fusions, such as ALK, RET, ROS1, and NTRK1, has significantly advanced lung cancer management." (PMID 39810398, 2025). "The samples obtained through EBUS-TBNA demonstrated solid quality parameters for RNA, which is crucial in lung cancer, given the therapeutic implications of certain fusions like ALK and ROS1." (PMID 40361881, 2025). "Discovery and drug development of new lung cancer‐related targets: EGFR, ALK, ROS1, RET, MET, BRAF inhibitors, etc." (PMID 40135802, 2025). "One of the recently studied molecular targets in oncology, especially glioblastoma and non‐small cell lung cancer (NSCLC), is ROS1." (PMID 40847660, 2025). "Specifically, in the field of lung cancer, this catalog advocates the inclusion of PD-L1, EGFR, ALK, ROS-1, KRAS, NTKR, RET, and MET." (PMID 40261489, 2025). "In our study, the safety profile of crizotinib was better compared to previous studies involving ROS1-positive and ALK-positive lung cancer individuals." (PMID 40142301, 2025). "The aim of the current study is to investigate the prevalence of alterations in the eight most frequently altered genes in lung cancer—BRAF, EGFR, KRAS, ALK, ROS1, HER2, PD-L1 and PIK3CA." (PMID 41153394, 2025). "These mutants are recapitulatedin CD74-ROS1 and SLC34A2-ROS1 fusions, two prevailing ROS1 rearrangementsin ROS1+ nonsmall cell lung cancers." (PMID 39361251, 2024). "We looked at the distribution of breakpoints in ALK, RET, ROS1, NTRK1, as well as other kinase genes known to generate oncogenic fusions in lung cancer, such as EGFR, ERBB4, MET, FGFR3, and EPHA245." (PMID 38877018, 2024).